RNU6-536P (RNA, U6 small nuclear 536, pseudogene)
Gene: Small nuclear RNA gene on chromosome 1 (42,569,033 to 42,569,139, forward strand). Ensembl gene ENSG00000200254.
Homologues: Orthologues: chimpanzee U6 (99% identical), macaque U6 (96% identical), rabbit U6 (93% identical), rat U6 (93% identical), mouse Gm25698 (92% identical), rabbit U6 (92% identical), rat U6 (85% identical). Paralogues in human: RNU6-1060P (93% identical), RNU6-19P (93% identical), RNU6-12P (93% identical), RNU6-13P (93% identical), RNU6-140P (93% identical), RNU6-16P (93% identical), RNU6-31P (93% identical), RNU6-32P (93% identical), RNU6-33P (93% identical), RNU6-761P (93% identical), RNU6-820P (93% identical), RNU6-854P (93% identical), and 1289 more.